RILPL2 (Rab interacting lysosomal protein like 2)
Description:
Involved in cell shape and neuronal morphogenesis, positively regulating the establishment and maintenance of dendritic spines (By similarity). Plays a role in cellular protein transport, including protein transport away from primary cilia (By similarity). May function via activation of RAC1 and PAK1 (By similarity).
Synonyms: RLP2; MGC7036; FLJ30380; FLJ32372
Tractability: Small molecule: a structure with a bound ligand is known. PROTAC: ubiquitination databases record sites on it; its protein half-life has been measured.
Gene: Protein-coding gene on chromosome 12 (123,409,714 to 123,436,684, reverse strand). Ensembl gene ENSG00000150977.
Subcellular location: Cytoplasm, cytosol; Cytoplasm, cytoskeleton, microtubule organizing center, centrosome; Cell projection, cilium
Subcellular location (Human Protein Atlas): Cytosol; Primary cilium; Vesicles
Gene Ontology:
Molecular function: identical protein binding; protein binding; dynein light intermediate chain binding; small GTPase binding; protein dimerization activity
Biological process: cilium assembly; epithelial cell morphogenesis; protein transport from ciliary membrane to plasma membrane
Cellular component: cytosol; centrosome; ciliary basal body; cilium; cytoplasm; membrane
Genetic constraint (gnomAD): Loss-of-function variants: 18 observed, 17.68 expected, observed/expected ratio (o/e) 1.02, 90% interval 0.7 to 1.51. The upper end of that interval is the gene's LOEUF score, 1.51, which puts it in group 6 of 6, group 1 being the genes least tolerant of losing a copy. Missense variants: 241 observed, 252.66 expected, observed/expected ratio (o/e) 0.95, 90% interval 0.86 to 1.06. Synonymous variants: 122 observed, 105.91 expected, observed/expected ratio (o/e) 1.15, 90% interval 0.99 to 1.34.
Homologues: Orthologues: chimpanzee RILPL2 (99% identical), macaque RILPL2 (91% identical), pig RILPL2 (81% identical), dog RILPL2 (80% identical), rat Rilpl2 (76% identical), mouse Rilpl2 (73% identical), guinea pig RILPL2 (71% identical), tropical clawed frog rilpl2 (56% identical), zebrafish rilpl2 (44% identical), Drosophila melanogaster Rilpl (24% identical), Caenorhabditis elegans rilp-1 (23% identical). Paralogues in human: RILPL1 (37% identical), RILP (25% identical), DZIP1L (19% identical), DZIP1 (16% identical).
Diseases named in the same sentence as RILPL2 in open-access papers:
RILPL2 is named in the same sentence as 10 diseases in open-access papers, as found by Europe PMC text mining. Sharing a sentence is not in itself a finding about the gene and the disease. The quoted sentences say what the papers report.
endometrial carcinoma (3 papers, 2021 to 2024). A malignant tumor arising from the epithelium that lines the cavity of the uterine body. "The last factor RILPL2 had prognostic value in different human cancers, such as endometrial cancer." (PMID 39588389, 2024). "In addition, RILPL2 could promote tumor progression via the TUBB3/PTEN pathway in breast cancer, and there were reported associations between RILPL2 and the infiltration patterns of multiple immune cell types in endometrial carcinoma." (PMID 39078518, 2024).
breast carcinoma (2 papers, 2021 to 2024). "The analysis of data obtained from online databases suggested that RILPL2 expressed lower in breast cancer tissues than that in adjacent tissues, and that low RILPL2 expression was prominently positively associated with TNM stage and differentiated grade." (PMID 34095226, 2021). "Overexpression of RILPL2 inhibited breast cancer cell proliferation and metastasis in vitro and in vivo." (PMID 34095226, 2021). "Besides, the interaction of exogenous RILPL2 with TUBB3 resulted in the downregulation of breast cancer cell proliferation and migration and upregulation of PTEN expression by promoting destabilization of TUBB3." (PMID 34095226, 2021). "However, relative studies indicated that RILPL2 showed a significant correlation with breast cancer by conducting series of literatures of RILPL2." (PMID 34095226, 2021).
non-small cell lung carcinoma (1 paper, 2024). A group of at least three distinct histological types of lung cancer, including non-small cell squamous cell carcinoma, adenocarcinoma, and large cell carcinoma. "Our previous bioinformatics analysis has revealed that Rab-interacting lysosomal protein-like 2 (RILPL2) is associated with tumor immune microenvironment in non-small cell lung cancer (NSCLC)." (PMID 39078518, 2024).
Obesity (1 paper, 2023). Accumulation of substantial excess body fat. "The RILPL2 is highly expressed in lymphocytic cells and artery, and have been associated to obesity-related traits, including BMI and waist-to-hip ratio, as well as peripheral arterial disease." (PMID 37033211, 2023).
Parkinson disease (1 paper, 2022). A progressive degenerative disorder of the central nervous system characterized by loss of dopamine producing neurons in the substantia nigra and the presence of Lewy bodies in the substantia nigra and locus coeruleus. "The Parkinson's-disease-associated LRRK2 kinase phosphorylates multiple Rab GTPases including Rab8 and Rab10, which enhances their binding to RILPL1 and RILPL2." (PMID 35776681, 2022).
cancer (3 papers, 2024 to 2026). A tumor composed of atypical neoplastic, often pleomorphic cells that invade other tissues. "Recent studies have suggested that the Rab-interacting lysosomal protein-like 2 (RILPL2) acts as a tumor suppressor and plays an inhibitory role in multiple human cancers." (PMID 42082464, 2026). "Compared with peri-cancer tissues, the RILPL2 expression in NSCLC tissues was significantly lower (P < 0.0001)." (PMID 39078518, 2024). "Compared with that in peri-cancer tissues, RILPL2 expression in NSCLC tissues was significantly lower (P < 0.0001)." (PMID 39078518, 2024).
tumor (3 papers, 2021 to 2026). "Within NSCLC, tumor cells exhibited diminished RILPL2 expression, a factor notably linked to both advanced tumor stage and unfavorable prognosis." (PMID 39078518, 2024). "By analyzing the data from TCGA, the expression of RILPL2 in the para-cancerous samples was remarkably higher than that in the tumor specimens (P < 0.001)." (PMID 34095226, 2021). "Decreased expression of RILPL2 is remarkably related to multiple factors, including age (P = 0.033), tumor histological type (P < 0.001), grade (P < 0.001) and clinical stage (P < 0.001)." (PMID 34095226, 2021). "The methylation level of RILPL2 in the normal samples was notably lower than that in the tumor samples (P < 0.001)." (PMID 34095226, 2021). "In this research, we first analyze the expression level of RILPL2 and summarize its prognostic roles, biological features, and correlation with tumor immune infiltration in EC patients, mainly according to the public data obtained from the Cancer Genome Atlas (TCGA) database." (PMID 34095226, 2021). "In addition, we further validated RILPL2 expression using our recruited cohort, and the result showed that RILPL2 in tumor samples was obviously lower than that of normal control (P = 0.013)." (PMID 34095226, 2021). "Our current research suggested that the expression of RILPL2 may regulate immune infiltration of multiple TIICs in the immune microenvironment of EC specimens, thus directly and/or indirectly regulating immune monitor and influencing progression of tumor." (PMID 34095226, 2021). "Moreover, correlation analysis of RILPL2 and tumor-infiltrating immune cells (TIICs) indicated that RILPL2 might play a critical role in regulating immune cell infiltration in EC and is related to immune response." (PMID 34095226, 2021).
infection (2 papers, 2013 to 2024). The state of being infected such as from the introduction of a foreign agent such as serum, vaccine, antigenic substance or organism. "Numerous host proteins were upregulated upon infection with Francisella, ranging from immune-related proteins to metabolic enzymes, including notably IRG1, MARCO, Rilpl2, C3, PcgF5, MT1, TRAF1, GBP2 and Fas." (PMID 38565565, 2024).
RILPL2 also shares sentences with these, for which no sentence is quoted: cervical cancer (1 paper); peripheral arterial disease (1).